BRAF (B-Raf proto-oncogene, serine/threonine kinase)
Diseases named in the same sentence as BRAF in open-access papers (continued):
Sharing a sentence is not in itself a finding about the gene and the disease.
melanoma (continued). "Overall, EPHB6G404S mutations were more frequently observed in melanomas without BRAF or NRAS mutations (16/202 melanomas, 7.9%), than co-occurring with either BRAF or NRAS mutations (10/264 melanomas, 3.8%, p-value = 0.04)." (PMID 27191502, 2016). "However, melanoma cell lines treated with these BRAF inhibitors have shown to rebound activation of phosphorylation of ERK (pERK) and escape from BRAF inhibition." (PMID 26884744, 2016). "We posit that combining BRAF inhibitors with drugs that target glutaminolysis or mitochondrial function may be an effective strategy to treat or prevent resistance to BRAF inhibitors in melanoma patients." (PMID 26365896, 2016). "Besides, in melanoma patients, both the BRAF wild type and BRAF mutant patients benefited in OS, and HRs (95%CIs) were 0.51, (0.45, 0.58), p < 0.001; 0.55, (0.44, 0.69), p < 0.001 respectively with not important heterogeneity (I2 = 2.7%; I2 = 8.0%)." (PMID 27542277, 2016). "Recent studies suggested that the combination of BRAF/MEK inhibition with immunotherapy could represent a promising strategy for the cure of melanoma." (PMID 27563819, 2016). "We have shown that athymic nude mice implanted with BRAF-mutated A375 and SK-MEL-28 melanoma cells treated with fisetin (45 mg/kg, body weight) and sorafenib (45 mg/kg, body weight) in combination more effectively reduced tumor growth compared to the individual agents alone." (PMID 26517521, 2016). "In summary, we have demonstrated that the combination of GSI-I with ABT-737 killed the bulk and the MICs of multiple melanoma samples, irrespective of the mutational status of BRAF, NRAS or NF-1." (PMID 27829238, 2016). "BVD-523 and GDC-0994, elicit cytotoxic effects in BRAF-V600E melanomas." (PMID 27655717, 2016). "However, while some studies have shown that inhibition of BRAF or MEK signaling in melanoma increases ER stress, yet conversely, others have demonstrated that inhibition of oncogenic BRAF or MEK resulted in a marked reduction in IRE1 and ATF6 based signaling." (PMID 27896217, 2016). "Thus, these two transition processes—resistance formation upon exposure to BRAF inhibitors and the more stochastic melanoma phenotypic switch—highly overlap." (PMID 27648299, 2016). "As treatment of metastatic melanoma increasingly involves combination therapies, it will be of great interest to define which combinations of miR-7-5p and targeted therapies (BRAF/MEK inhibitors) or immunotherapies are most effective or yield synergistic anti-melanoma effects." (PMID 27203220, 2016). "Therefore, more sensitive tools for monitoring of response and resistance to BRAF/MEK targeted therapy is of interest in order to optimize treatment of advanced BRAF V600 mutant melanoma." (PMID 27095081, 2016). "In addition, many studies have shown that IGF-1R depletion reduces the survival of BRAF-mutant and wild-type melanoma cells, and increases their chemosensitivity." (PMID 27764776, 2016). "The IdyllaTM BRAF Mutation Test, CE IVD, on the IdyllaTM platform (Biocartis, Mechelen, Belgium) was successfully launched for the fast and accurate detection of BRAF V600 mutations in melanoma patients, directly on FFPE samples." (PMID 27685259, 2016). "The current treatments of melanoma include BRAF and MEK inhibitors, or immunotherapy drugs." (PMID 27829238, 2016). "Vemurafenib is approved for the treatment of BRAF-mutant melanoma." (PMID 27096871, 2016). "We propose that intrinsic and adaptive resistance to BRAF inhibition in BRAFV600E melanomas occurs by multiple mechanisms that differ substantially, dependent on the broader genetic and epigenetic landscape of the cancer cells that shape the underlying architecture of cell signaling networks." (PMID 26673621, 2016). "Interestingly, depletion of F4/80 and CD11b positive macrophages enhances the antitumor activity of BRAF inhibitors on mouse melanoma tumors." (PMID 27708249, 2016).
melanoma (continued). "Furthermore, mAb W9 delays the development of BRAF inhibitor resistance in melanoma cells with mutant BRAF." (PMID 27461275, 2016). "Therefore, the longer elimination half-life of oral ixazomib makes it a promising agent for a combined treatment of BRAF V600E mutant melanoma with ixazomib and IFN-α." (PMID 27783987, 2016). "Because IGF-1R, FGFR1, and EGFR have been shown to play major roles in melanoma progression through autocrine signaling, and EGF-R, PDGFRβ, and IGF-1R have been implicated in resistance mechanisms to BRAF V600E targeted therapies, we were interested in validating these results." (PMID 27102439, 2016). "We established a BRAF‐mutant melanoma cell line expressing an ERK/MAP kinase ‘biosensor’." (PMID 26414886, 2016). "Mutations in the BRAF and KIT genes in subsets of melanoma have been reported." (PMID 27124046, 2016). "BRAF V600 mutant circulating cell-free tumor DNA (BRAF V600mut ctDNA) could serve as a specific biomarker in patients with BRAF V600 mutant melanoma." (PMID 27095081, 2016). "Possible cooperative interactions between activation of BRAF/MEK/ERK and RASA1/R-Ras/Ral-A pathways may explain the observed decreased overall survival of melanoma patients, who have low levels of RASA1 expression and BRAF mutations." (PMID 26993606, 2016). "Moreover even in BRAF mutant melanoma the vast majority of patients still develop progressive disease after combined BRAF and MEK-inhibition." (PMID 27447557, 2016). "Mutations in BRAF and N-RAS account for roughly 50% and 20% of melanoma patients, respectively." (PMID 27698666, 2016). "Collectively, our study demonstrated that miR-7 could reverse the resistance to BRAF inhibitors in certain vemurafenib resistant melanoma cell lines." (PMID 27448964, 2016). "However, between 2011 and 2014 the FDA and the EMA have approved the use of vemurafenib (PLX4032) and dabrafenib (GSK2118436) for the treatment of BRAF mutant melanoma patients." (PMID 27200346, 2016). "To confirm that this method could identify regions known to be biologically important in melanoma, we examined those hotspots with high numbers of mutations and a high proportion of samples; pleasingly this identified TERT and BRAF SNVs as striking outliers." (PMID 27611953, 2016). "Advances in targeted BRAF and MEK in patients whose melanoma harbor mutations in BRAF and the emergence of T cell checkpoint inhibitors alone and in combination have revolutionized the therapeutic approach to advanced melanoma." (PMID 27660707, 2016). "Importantly, independent reports support the in vivo relevance of this mesenchymal de-differentiation state in BRAF inhibitor-naive melanoma." (PMID 27648299, 2016). "Next, we tested, whether exogenous expression of CRAF R391W can functionally replace BRAF V600E in a melanoma cell line." (PMID 27273450, 2016). "The rationale for combining BET and BRAF inhibitors in melanoma revolves around the hypothesis that both might trigger cell cycle arrest and apoptosis through different mechanisms of action." (PMID 27169980, 2016). "Moreover, primary resistance or adaptive tumor response to BRAF inhibition in melanoma include upregulation of receptor tyrosine kinases." (PMID 27713119, 2016). "Interestingly, all of the patients with a partial response or durable stable disease had wild-type BRAF melanoma." (PMID 27056178, 2016). "This further emphasizes the relevance of the BRAF/MITF connection for melanoma development." (PMID 27200346, 2016). "These melanomas were BRAF wild-type and diagnosed from atypical melanocytic lesions." (PMID 27042173, 2016). "Compared to co-targeting of mutant BRAF and PI3K/mTOR, the association of a MEK1/2 and a PI3K/mTOR inhibitor was more effective in the activation of Bax and of caspase-3 and in the induction of caspase-dependent melanoma apoptosis." (PMID 26678033, 2016).
melanoma (continued). "The importance of ER homeostasis in melanoma is highlighted by the constitutive upregulation of certain ER-resident chaperones, such as GRP78, and their correlation with upstream, disease initiating, NRAS, or BRAF oncogenic mutations." (PMID 27896217, 2016). "KIR and HLA genotyping may be useful in determining the risk of developing uveitis patients either receiving immunostimulatory therapy for cancer or MEK/BRAF treatment for malignant melanoma in particular." (PMID 27490240, 2016). "We next examined if the effects of SGI-1776 in melanoma preclinical models could be further enhanced in the presence of a BRAF inhibitor." (PMID 27448973, 2016). "In contrast, NRAS mutations were more common in melanomas arising from the arm/leg extremities (45.2%) compared with BRAF mutant (30.0%) or melanomas without mutations detected (33.7%) for this location." (PMID 27191502, 2016). "We found that while melanoma cell lines expressing mutant KIT migrated over 7mm away from the seeding area after 2 weeks of 3D culture, BRAF mutant melanoma cells and wild type melanocytes only migrated less than 4mm from the seeding site at 2 weeks (2-sided student t-test; p<0.05)." (PMID 27322141, 2016). "Dabrafenib is a reversible ATP-competitive inhibitor of V600E- and V600K-mutant BRAF that was approved in 2013; however, the median progression-free survival in melanoma patients treated with dabrafenib was found to be shorter than that reported with vemurafenib." (PMID 27833586, 2016). "Thus, PAX3, a well-known transcriptional regulator of MITF, is upregulated during MAPKi treatment, which is also seen within 48 hr in a panel of BRAF mutant melanoma cell lines." (PMID 26977879, 2016). "al. showing synergy between PI3K and PDK1 inhibitors in BRAF mutant melanomas." (PMID 26673621, 2016). "BRAF inhibitors often show skin-hyperproliferative side effects in melanoma patients." (PMID 27476449, 2016). "This is the same pathway targeted by vemurafenib in BRAF-mutant melanoma." (PMID 26857260, 2016). "Together, these stress responses alleviate sufficient proteotoxic stress to allow melanoma cells to adapt and evolve molecular mechanisms that circumvent BRAF inhibition and reactivate MEK-based signaling, ultimately leading to increased resistance to proteotoxic stress." (PMID 27896217, 2016). "We estimated an EC80 for inducing ERK activation for each BRAFi, which was then compared to the IC80 for growth inhibition of BRAF-mutant melanoma cells to derive a paradox index as a means of quantifying a therapeutic window of high clinical efficacy and minimal paradoxical ERK activation." (PMID 27028853, 2016). "We hypothesize that the intensity of BRAF V600E expression could be correlated to tumor stage aggressiveness at diagnosis in melanoma patients." (PMID 27863476, 2016). "In summary, RASA1 plays tumor suppressive roles in melanomas with BRAF activation." (PMID 26993606, 2016). "Further delineation of the exact mechanism of cell death activating pathways induced by proteasome inhibitors and the mechanisms of proteasome inhibitor resistance by BRAF wild-type melanoma may help identify future therapeutic anti-tumor molecular targets." (PMID 27783987, 2016). "This behaviour is independent of the mutation status of the melanoma cell lines, since the same observation was made using cell lines that were wild-type and cell lines carrying the V600E BRAF mutation." (PMID 27172792, 2016). "The role of the BRAF/ERK pathway on CD70 expression in melanoma cells was also investigated here because this pathway is essential in melanoma progression and metastasis, and because pharmacological inhibitors have a strong but often transitory efficacy against these tumors." (PMID 26828592, 2016).
melanoma (continued). "To identify potential target(s) for therapeutic intervention in a significant proportion of melanomas that harbor dual mut-BRAF and MITF amplification (MITFAmp), we developed a multi-step integrative target identification approach—drug-effected integrative identification of target(s) (DEFINIT)." (PMID 26962685, 2016). "In this translational research study we analyze the value of longitudinal quantitative measurement of BRAF V600mut ctDNA from plasma as a therapeutic monitoring tool for patients with advanced BRAF V600 mutant melanoma treated with the BRAF/MEK inhibitors dabrafenib and trametinib." (PMID 27095081, 2016). "The V600 mutations account for the majority of BRAF mutations and are observed in Langerhans cell histiocytosis (LCH), Erdheim-Chester disease (ECD), melanoma, papillary thyroid carcinoma, colorectal cancer, hairy cell leukemia (HCL), and chronic lymphocytic leukemia (CLL)." (PMID 27094161, 2016). "Importantly, this finding suggests that MAP kinase pathway inhibition can – in principle –constitute a viable treatment option for a subset of BRAF/NRAS wild type melanomas." (PMID 27273450, 2016). "Indeed, preclinical data showed that the combination of anti-PD-1 or anti-PD-L1 with BRAF inhibition enhanced antitumor responses in a BRAF/PTEN inducible melanoma model, thus warranting clinical studies." (PMID 27847783, 2016). "Altogether, these experiments indicate that (I) Pin1 correlates with FOXM1 expression and activity in malignant melanoma, (II) Pin is causally linked to FOXM1 activity through physical binding on MEK/ERK target sites and (III) oncogenic BRAF stimulates the Pin1-FOXM1 interaction through MEK." (PMID 26279295, 2016). "Moreover, in BRAF V600E melanoma cell lines, vemurafenib inhibits 4E-BP1 phosphorylation, thus promoting its binding to eIF4E." (PMID 26767073, 2016). "Combining the BRAF inhibitor, dabrafenib, with the MEK inhibitor, trametinib, improves progression-free survival in melanoma patients with BRAF V600 mutations, and the same combination has demonstrated preliminary benefit in patients with metastatic NSCLC harboring the BRAF V600E mutation." (PMID 27608848, 2016). "Another major drawback of current melanoma treatments is the lack of therapeutic options for patients who are WT for common mutations in BRAF, NRAS or NF-1 (Triple-WT)." (PMID 27829238, 2016). "Indeed, in patients receiving this therapy the degree of MAPK inhibition is comparable to that achieved in BRAF-mutant melanoma patients receiving RAF monotherapy." (PMID 27308562, 2016). "However, the combination of ixazomib with IFN-α significantly enhanced ixazomib's ability to induce apoptotic cell death in BRAF V600E mutant and BRAF wild-type human melanoma tumor cells." (PMID 27783987, 2016). "As a selective BRAF inhibitor, vemurafenib is used for patients with malignant melanoma." (PMID 27388711, 2016). "Melanoma cell intrinsic resistance to BRAF inhibitors seems to be diverse and independent resistance mechanisms may even develop in parallel in different tumour lesions." (PMID 26414886, 2016). "In order to determine whether honokiol DCA had activity against vemurafenib resistant melanoma, we assessed the ability of honokiol DCA in vivo against LM36, a BRAF mutant melanoma and LM36R, a vemurafenib resistant clone of LM36." (PMID 26871475, 2016). "IT treatment (2.5, 5, 10, 20, 40 and 80 μM; 24, 48, and 72 h) significantly induced cytotoxicity to human melanoma A375S (parental cells, sensitive to BRAF inhibitor), A375R (resistant to BRAF inhibitor), A2058, and MEWO cells in a time- and dose-dependent manner." (PMID 27323414, 2016). "PI3K inhibitors have previously shown activity in melanoma, regardless of BRAF mutation status, in response to PI3K family members being highly expressed in metastatic melanoma, and PTEN being frequently deleted." (PMID 26137449, 2015). "Approximately 50% of melanomas depend on mutant BRAF for proliferation, metastasis and survival." (PMID 26116372, 2015).
melanoma (continued). "Consequently, similar to the observations in melanoma, the development of combinatorial treatment using BRAF and/or MEK inhibitors with immunotherapy appears to hold promise for CRC patients." (PMID 26299805, 2015). "Our data firmly validates the prognostic significance of the gene expression phenotypes and provides novel evidence that the gene expression phenotypes may predict benefit from molecular targeted therapies in advanced stage melanoma beyond BRAF status." (PMID 25909218, 2015). "Several recent reports demonstrated that PD-L1 expression did not correlate with BRAF mutational status in melanoma and lung adenocarcinomas." (PMID 26305724, 2015). "In this study we analysed the ctDNA in BRAF and NRAS-mutated melanoma patients at baseline (n = 48) and within 8 weeks of treatment initiation (n = 25) to determine whether ctDNA correlates with treatment response and clinical benefit." (PMID 26524482, 2015). "Gender distribution, age, site and Breslow thickness of primary melanoma was not statistically associated with BRAF or NRAS mutational status." (PMID 26305188, 2015). "However, their joint addition significantly increased melanoma cell death, partly attenuated in the BRAF-mutant A375 cells." (PMID 26356671, 2015). "The CGH data showing that RICTOR is also amplified in BRAF mutated melanoma, suggest that RICTOR could also cooperate with oncogenic BRAF." (PMID 26356562, 2015). "However, this analysis, carried out in eight melanoma cell lines, showed the preferential amplification of mutant BRAF as a mechanism of an increased ratio of mutant/WT BRAF." (PMID 26141748, 2015). "The melanoma cell lines had various statuses of the most common mutations in BRAF (BRAFV600E) and NRAS (NRASQ61R), but harboured no mutation in the other key components of the PI3K pathway, including PIK3CA, PTEN, and PIB5PA." (PMID 26573229, 2015). "Targeting Aurora B kinase potentially has a dual antitumor role, by directly inhibiting migration and growth of cells and as enhancer of vemurafenib efficacy in BRAF(V600K) melanoma and of nab-paclitaxel based chemotherapy in BRAF wild type and mutated melanoma." (PMID 25623468, 2015). "Interestingly, when compared to their use as single agents, the combination of BAY 87-2243 and vemurafenib induced augmented tumor regression in nude mice bearing BRAF mutant melanoma xenografts." (PMID 26500770, 2015). "As opposed to the results obtained in melanoma, no alterations were detected in the 27 cases of nevi available, thus excluding a causal link between BRAF mutations and chromosomal instability in melanocytic tumors." (PMID 26141748, 2015). "If this combination therapy is proven effective, it could potentially replace palliative radiation therapy as the preferred therapeutic modality, especially in BRAF inhibitor-naive patients with BRAF-mutant melanoma who also have extracranial metastases." (PMID 25962795, 2015). "Whether PGC-1α is re-expressed in recurrent melanoma and contributes to the fast progression after BRAF inhibitor resistance development is currently unknown." (PMID 26000250, 2015). "BRAF mutations leading to constitutive activation of the RAS/RAF/MEK/ERK pathway and increased cell cycle progression, differentiation, survival, migration, and angiogenesis are reported in 40–50% of melanoma cases." (PMID 26137449, 2015). "The most common BRAF and RAS mutations of melanoma are associated with increased miR-21 expression." (PMID 26116372, 2015). "Moreover, our results suggest that combination of BRAF inhibitors with Mcl-1 targeted therapies were successful in overcoming acquired resistance in melanoma in vitro and in vivo." (PMID 26497853, 2015). "For instance, Wilmott and colleagues reported different subclones in tumor tissue from a single metastatic site in a BRAF-mutant melanoma patient, following progression of disease after seven months of treatment with the BRAF inhibitor vemurafenib; one clone had an additional NRAS mutation." (PMID 25886620, 2015).